IL6 (interleukin 6)
Diseases named in the same sentence as IL6 in open-access papers (continued):
Sharing a sentence is not in itself a finding about the gene and the disease.
Obesity (continued). "Obesity per se results in a chronic state of low-grade systemic inflammation, mediated by excess adipocyte production of pro-inflammatory cytokines including interleukin-6 (IL-6), tumour necrosis factor-α (TNF-α), monocyte chemoattractant protein-1 (MCP-1) and interleukin-8 (IL-8)." (PMID 23418448, 2013). "The pro-inflammatory cytokines TNFα and IL-6 have been shown to trigger phosphorylation of IRS-1, thus exerting an inhibitory action on insulin signaling; accordingly, genetic ablation either of TNFα or of its receptor can improve insulin resistance caused by obesity in rodent models." (PMID 23698776, 2013). "Thus, obesity-induced IL-6 secretion may reflect a mechanism to increase insulin production in the obese insulin resistant state." (PMID 24455420, 2013). "With adipose tissue expansion in obesity, there is a marked increase in the synthesis and release of proinflammatory factors (e.g. TNFα, IL-6, IL-8 and MCP-1), and this may contribute to the elevated circulating levels seen as well as to local tissue inflammation." (PMID 23637889, 2013). "It is widely accepted that obesity is characterized by evidence of a chronic, low-grade inflammatory process, as manifested by elevated circulating levels of acute phase proteins and cytokines, such as tumor necrosis factor α (TNFα), interleukin 1 (IL-1), and IL-6." (PMID 23967297, 2013). "Though Il6-KO mice may exhibit a lean phenotype at young age, it has been reported that Il6 deficiency leads to obesity in the maturity without affecting feeding behaviour." (PMID 24015235, 2013). "Overall, IL-6 may play a pivotal role in metabolic diseases, including obesity." (PMID 24455420, 2013). "In this context, the finding that tumor necrosis factor-α (TNF-α) and IL-6 are overexpressed in the adipose tissue of obese mice and humans and when administered exogenously leads to insulin resistance, provided the first clear link between obesity, diabetes, and chronic inflammation." (PMID 24151494, 2013). "As IL-6 is produced and secreted from adipose tissue, which in turn stimulates CRP production from the liver, one would expect elevated levels of both indicators in the presence of obesity, increasing the likelihood of significant associations with clustered cardiometabolic risk." (PMID 23984329, 2013). "As the regulation of IL-6 might be substrate dependent, it is possible that the difference in IL-6 response observed in the present study could reflect an acceleration of epigenetic modifications in obesity and type 2 diabetes." (PMID 22761857, 2012). "Furthermore, IL-6 knockout mice develop obesity at the young age of 6 months." (PMID 22518191, 2012). "With our current data, it is not possible to conclude whether the dysregulation of IL-6 signaling in obesity and type 2 diabetes is linked or whether it represent two independent phenomena." (PMID 22761857, 2012). "The increase in obesity-associated OS is probably due to the presence of excessive adipose tissue itself, because adipocytes and preadipocytes have been identified as a source of proinflammatory cytokines, including TNF-α, IL-1, and IL-6; thus, obesity is considered a state of chronic inflammation." (PMID 21686173, 2011). "In addition, IL-6 inhibits adiponectin gene expression in cultured adipocytes, which may exacerbate obesity-related hypertension." (PMID 21410966, 2011). "Even thought that IL-6 is closely associated with TNF-α in exercise, in the present work we chose CRPhs as marker of chronic low-grade inflammation, because CRP is positively correlated with obesity, insulin resistance and has been shown to better predict CVD than other cytokines." (PMID 22174491, 2011). "On the other hand, increased leptin levels are associated with increased concentrations of other proinflammatory cytokines such as IL-1, IL-6, IL-8, TNFα, and prostaglandin E2, which may provide more specific and selective approaches for pharmacologic intervention in obesity-induced osteoarthritis." (PMID 20604941, 2010).
Obesity (continued). "Increased mRNA expression of TNF-α, IL-1 and IL-6 has been reported in the kidney of streptozotocin-induced type 1 diabetic rats, a model associated with much higher levels of plasma glucose and no obesity." (PMID 20490358, 2010). "Cytokines such as tumour necrosis factor-alpha and interleukin-6 may be the biological link between obesity and insulin resistance, and are raised in Indian urban slum dwellers (often recent migrants), lowest in rural villagers, with intermediate levels among the urban middle class." (PMID 16533387, 2006). "Additionally, IL-6 depletion selectively improves hepatic insulin action in obesity." (PMID 16787541, 2006). "Consistent with previous studies, we found that obesity promoted a shift toward M1 macrophage dominance, characterized by increased circulating pro-inflammatory cytokines including TNF-α, IL-6, and IL-1β." (PMID 41556049, 2026). "Interestingly, a meta-analysis of 50 lifestyle programs found that combining physical activity/exercise with dietary/nutritional changes is likely to lower CRP, IL-6, and IL-1β concentrations, and may also reduce IL-8 in healthy children and adolescents who have overweight or obesity." (PMID 41515266, 2026). "Biomarkers, such as ferritin, leptin, resistin, interleukin-6 (IL-6), insulin, tumor necrosis factor-alpha and plasminogen activator inhibitor-1 (PAI-1), play crucial roles in the pathophysiology of obesity." (PMID 41011232, 2025). "Chronic inflammation, which is particularly prevalent in obesity, generates a continuous influx of cytokines, such as TNF-α and IL-6, that maintain a self-reinforcing cycle of NF-κB activation and oxidative stress." (PMID 40002389, 2025). "The effect is bidirectional: obesity has been shown to reduce BDNF levels, and SCZ, by increasing IL-6 levels, also contributes to its reduction." (PMID 41007867, 2025). "Individuals with obesity tend to have higher serum levels of tumor necrosis factor-alpha (TNF-α) and interleukin-6 (IL-6)." (PMID 41156096, 2025). "Obesity indirectly regulates de novo lipogenesis of fatty acids by controlling downstream AKT1 and SREBF1 through IL6." (PMID 39928768, 2025). "The chronic inflammatory state that characterizes obesity was reflected in the MS mice by increased TNF-α, IFN-γ, and IL-6 plasma levels." (PMID 40710566, 2025). "Chemerin also contributes to obesity-related inflammation by recruiting macrophages, dendritic cells, and NK cells and correlates with pro-inflammatory markers such as TNF-α, IL-6, and hs-CRP." (PMID 40564199, 2025). "Dairy products and dairy proteins have demonstrated efficacy in reducing inflammatory markers, including CRP, IL-6, TNF-α, and MCP-1, in individuals with obesity and overweight conditions." (PMID 40216734, 2025). "In HFD-fed mice, adipocyte-specific IL-6-gp130 signaling induced FFA release from visceral adipocytes, promoting obesity-induced hepatic insulin resistance and steatosis." (PMID 40864559, 2025). "Studies in both humans and animals have demonstrated that obesity-induced inflammatory changes in adipose tissue lead to elevated levels of proinflammatory cytokines, including TNF-α, IL-6, and monocyte chemoattractant protein-1 (MCP-1)." (PMID 40599559, 2025). "In particular, TNF-α, IL-6, and CRP are reported to be significantly high in the circulation of pregnant women with obesity or GDM." (PMID 40278381, 2025). "Inflammation, particularly involving interleukin-6 (IL-6) and tumor necrosis factor-alpha (TNF-α), plays a crucial role in the pathogenesis of obesity and T2DM." (PMID 40842495, 2025). "Visceral adipose-derived IL-6 stimulates hepatic CRP production via STAT3 activation, creating a 2- to 3-fold increase in circulating CRP levels observed in obesity." (PMID 40699756, 2025). "These include cytokines crucial in the pathophysiology of obesity, such as tumor necrosis factor alpha (TNF-α), interleukin-6 (IL-6), and interleukin-1β (IL-1β), thus perpetuating the chronic low-grade inflammatory state." (PMID 41153608, 2025).
Obesity (continued). "Pro-inflammatory cytokines, including TNF-α, IL-6, and IFN-γ, exhibit elevated levels in obesity cases and disrupt adipogenesis by impairing the function of transcriptional regulators such as PPARγ and C/EBPα." (PMID 40002389, 2025). "When infected with influenza A, the adipose tissue of two mouse models of obesity produced increased levels of MCP-1, TNFα, IL-6, and TGFβ." (PMID 40386706, 2025). "In individuals with obesity or MetS, Breg cells tend to reduce the number of IL-10 secreting cells, increase autoantibody production, and increase the number of TNF-α and IL-6-producing cells." (PMID 40696355, 2025). "In obesity, hypertrophied adipocytes become metabolically dysregulated, secreting elevated levels of inflammatory cytokines including TNF-α, IL-6, and MCP-1, which contribute to systemic insulin resistance, endothelial dysfunction, and myocardial fibrosis." (PMID 41374408, 2025). "Researchers found that individuals with severe obesity had higher levels of proinflammatory markers such as CRP and IL-6, oxidized LDL, and worse thickness and stiffness in vessels." (PMID 40703531, 2025). "In contrast, EATs of patients with obesity or T2DM have higher numbers of CD4+ T and B cells and pro-inflammatory cytokines, such as IL-1, IL-6, TNF-α and IFN-γ." (PMID 40592472, 2025). "The findings revealed that, in comparison to normal weight children, several cytokines, including MIP-1b, PDGF-BB, IP-10, IL-6, IL-9, and TNF-β, exhibited elevated levels in the serum of children with obesity." (PMID 40519917, 2025). "In obesity, adipose tissue hypertrophy leads to macrophage infiltration and the production of pro-inflammatory cytokines, such as TNF-α and IL-6, which play central roles in chronic inflammation and insulin resistance." (PMID 40862455, 2025). "Pearson's correlation showed that IL‐6 and OSM concentrations in serum and hippocampal tissue of the obesity group mice were positively correlated with interleukin‐6 receptor subunit beta concentrations." (PMID 40958408, 2025). "As obesity is a state of IR, adipose tissue can secrete tumor necrosis factor (TNF‐α), interleukin‐6 (IL‐6), interleukin‐1β (IL‐1β) and other substances." (PMID 41245183, 2025). "Adipose tissue in obesity functions as an endocrine organ, secreting pro-inflammatory cytokines such as tumor necrosis factor-alpha (TNF-α), interleukin-6 (IL-6), and leptin while suppressing anti-inflammatory adiponectin levels." (PMID 40243559, 2025). "The main inflammatory players in obesity are pro-inflammatory cytokines such as TNF-α, IL-6, and C-Reactive Protein (CRP), as well as adipokines such as leptin, adiponectin, resistin, among others secreted by adipose tissue." (PMID 41373779, 2025). "Pro-inflammatory macrophages, activated by obesity-related stress, secrete cytokines such as TNF-α and IL-6, which trigger the canonical NF-κB signaling cascade." (PMID 40282189, 2025). "For example, obesity was characterized by systemic low-grade chronic inflammation, marked by elevated levels of CRP, IL-6, IL-8, and tumor necrosis factor-α (TNF-α) in the serum." (PMID 40612555, 2025). "Obesity triggers systemic inflammation (e.g., increased CRP, IL-6, and leptin) and reduces vitamin D availability, both of which are implicated in MS development." (PMID 40909065, 2025). "In males with obesity, concentration of GRO-α was significantly lower (p<0.05) and IL-6 and IL-22 showed a lower trend in vaccinated mice." (PMID 41488663, 2025). "Our analysis identified multiple potential targets of OJ extract in obesity-induced muscle atrophy, with core nodes including AKT1, IL6, and CASP3." (PMID 41470891, 2025). "Inflammatory biomarkers showed the expected directional trends, with higher mean concentrations of IL-6, β-defensin-2, ferritin, and hs-CRP in the obesity group compared with controls; however, these differences were not significant." (PMID 41614735, 2025).
Obesity (continued). "In response to elevated IL-6 levels, the liver triggers the secretion of high-sensitivity C-reactive protein (hs-CRP), a key marker of inflammation in obesity." (PMID 40564199, 2025). "IL-6 plays a dual role: while acutely anti-inflammatory via STAT3, chronic elevation in obesity promotes hepatic acute-phase responses and synergizes with IL-1β to induce β-cell endoplasmic reticulum (ER) stress." (PMID 40699756, 2025). "Among the proinflammatory cytokines discussed, IL-6, CRP, and TNF-α appear to be the most promising candidates as potential biomarkers for depression, particularly in the context of obesity, where their levels are also elevated." (PMID 40507778, 2025). "Leptin, in particular, is implicated in the upregulation of inflammatory cytokines such as IL-6 and TNF-α, contributing to the low-grade inflammation characteristics of obesity." (PMID 39857920, 2025). "Pro-inflammatory cytokines (e.g., TNF-α, IL-1β, IL-6, MCP-1) contribute to metabolic disorders such as obesity and diabetes." (PMID 40573106, 2025). "Obesity promotes a pro-inflammatory environment by increasing TNF-α, IL-6, IL-1, leptin, and resistin levels that reach the bloodstream and generate a systemic inflammatory state." (PMID 40067600, 2025). "Emerging research points to shared mechanisms among IBS, obesity, T2D, and cancer, with chronic inflammation as a unifying theme: IBS involves mucosal immune activation, while obesity and T2D are marked by elevated cytokines such as TNF-α and IL-6." (PMID 41514860, 2025). "Obesity and psoriasis exhibit similar systemic inflammatory profiles, with elevated serum levels of cytokines such as TNF-α, IL-6, and IL-12." (PMID 40219010, 2025). "A total of 18 RCTs (15 two-arm, 2 three-arm, and 1 four-arm) reported improvements in IL-6 outcome indicators for patients with T2DM and overweight or obesity." (PMID 40842495, 2025). "Peripheral blood samples from validation cohort including 44 healthy children and 44 obesity children were used to evaluate concentration levels of MIP-1b, PDGF-BB, IP-10, IL-6, IL-9 and TNF-β." (PMID 40519917, 2025). "In contrast, in T2D and obesity, EAT undergoes adipocyte hypertrophy and inflammatory activation, with increased secretion of TNF-α, IL-6, MCP-1, and leptin." (PMID 41375727, 2025). "Obesity is a state of chronic inflammation, characterized by elevated levels of circulating inflammatory factors such as TNF-α and IL-6 (Hotamislig and il, 2006)." (PMID 41278194, 2025). "Obesity-related adipose tissue secrets pro-inflammatory cytokines such as tumor necrosis factor-alpha (TNF-α), interleukin-6 (IL-6), and C-reactive protein (CRP)." (PMID 40981180, 2025). "Adipose tissue dysfunction in obesity triggers the release of pro-inflammatory cytokines (e.g., TNF-α, IL-6) and reduces adiponectin, an anti-inflammatory and insulin-sensitizing adipokine." (PMID 40181314, 2025). "The findings revealed that, in comparison to the control group, the levels of Interleukin‐6 receptor subunit beta, IL‐6, and OSM in the serum and hippocampal tissue of mice in the obesity group were significantly reduced (p < 0.01)." (PMID 40958408, 2025). "Leptin levels are typically elevated in individuals with obesity, leading to an upregulation of pro-inflammatory cytokines like TNF-a and IL-6." (PMID 40558305, 2025). "One of the earliest and most critical alterations observed in obesity is hypothalamic inflammation, characterised by microglial activation, astrogliosis, and the secretion of proinflammatory cytokines such as TNF-α and IL-6." (PMID 41226484, 2025). "Results remained robust after adjustment for other inflammation (interleukin 6), renal and cardiac (creatinine, NT-proBNP, cardiac troponin T) biomarkers, and after excluding participants with CVD, type 2 diabetes, and obesity." (PMID 40448790, 2025). "The results of network molecular pharmacology indicated that IL‐6 and TNF‐α were key targets for ECT in regulating obesity." (PMID 40772014, 2025).
Obesity (continued). "After adjustment for age, sex, obesity, active cancer, D-dimer, CRP, and IL-6, severe lung involvement remained a strong independent predictor of in-hospital mortality (OR 4.46; 95% CI 1.55–12.86; p = 0.006)." (PMID 41463074, 2025). "Additionally, obesity is associated with a state of chronic low-grade inflammation, wherein pro-inflammatory cytokines, such as tumor necrosis factor-alpha (TNF-α), interleukin-6 (IL-6), and interleukin-1 (IL-1), are upregulated, further exacerbating metabolic dysregulation." (PMID 39974837, 2025). "For instance, interleukin-6 (IL-6) and tumor necrosis factor-alpha (TNF-α) are pro-inflammatory cytokines released from PVAT in conditions such as obesity." (PMID 40642747, 2025). "Obesity activates various proinflammatory pathways, which includes elevated level of cytokines such as tumor necrosis factor-α (TNF-α), interleukin-6 (IL-6), C-reactive protein (CRP), plasminogen activator inhibitor-1 (PAI-1), and leptin." (PMID 40893881, 2025). "The initial models included age, chronic kidney disease, hypertension, obesity, dependence in basic activities of daily living (BADL), fever at presentation, desaturation, as well as SFC and IL-6 levels." (PMID 40889097, 2025). "Obesity, particularly visceral adiposity, is characterized by chronic low-grade inflammation, driven by proinflammatory cytokines such as TNF-α and IL-6." (PMID 41001130, 2025). "Aerobic and resistance training programs up to 4 months resulted in a decrease in scWAT inflammatory gene expression such as IL-6, IL-8, and TNF-α and CD36 macrophage marker in patients with obesity or those over 71 years of age." (PMID 40522819, 2025). "TNF-α levels are inversely correlated with insulin sensitivity, while IL-6 and IL-1β inhibit insulin receptor substrate 1 (IRS-1); moreover, elevated levels of leptin in women with pregestational obesity contribute to insulin resistance." (PMID 41374008, 2025). "Secondly, IL-1β, IL-6, TNF-α, and IL-18 are overexpressed in obesity, contributing to the development of nephropathy by promoting inflammation." (PMID 40703753, 2025). "Several key inflammatory markers have been reported to involve in obesity-induced inflammatory responses, including CRP, IL-6, and tumor necrosis factor-α (TNF-α)." (PMID 40568560, 2025). "There is a feedback loop explaining the increased production of multiple inflammatory cytokines (IL-6, IL-12, TNF-α) from leptin and the increased expression of leptin from others (e.g., IL-1, TNF-α), leading to a chronic inflammatory state due to obesity." (PMID 41227378, 2025). "In contrast, resistin levels are elevated in obesity and have been shown to promote insulin resistance and the release of pro-inflammatory cytokines such as TNF-α and IL-6." (PMID 41155642, 2025). "The significantly increased levels of IL‐1β, IL‐6, and TNF‐α, in HFD‐fed mice are consistent with the well‐established link between obesity and chronic low‐grade inflammation, often referred to as “metaflammation”." (PMID 41245183, 2025). "In individuals with obesity-related insulin resistance, hypertrophied adipocytes exhibit increased secretion of pro-inflammatory cytokines, such as TNF-α, IL-6, and IL-1β, all of which impair insulin signaling by activating NF-κB and JNK pathways." (PMID 40563357, 2025). "Elevated levels of inflammatory mediators, such as tumor necrosis factor alpha (TNF-alpha), interleukin-6 (IL-6), and C-reactive protein (CRP), are observed in obesity." (PMID 40218888, 2025). "Moreover, Obesity may increase inflammatory factors, IL-6, IL-8, and IL-1β, thereby increasing IR." (PMID 40162320, 2025). "Recent studies have explored the effects of high-fat diets on gene expression in adipose tissue, revealing specific gene alterations that contribute to obesity and insulin resistance such as ADIPOQ, CD36, PPARG, and IL6." (PMID 40408066, 2025).